CCL4 (C-C motif chemokine ligand 4)
Diseases named in the same sentence as CCL4 in open-access papers (continued):
Sharing a sentence is not in itself a finding about the gene and the disease.
viral infection (continued). "We observed increased level of inflammatory mediators (IL-1α, IL-1β, IL-6, MIP-1α (CCL3), MIP-1β (CCL4), RANTES (CCL5), MCP-1 (CCL2)) following H5N3 virus infection at 4, 8 and 20 hpi compared to cells infected with the H1N1/WSN, H5N2 and H9N2 viruses." (PMID 28558796, 2017). "Increased levels of CCL4 (Japanese encephalitis virus, West Nile virus [WNV]) and IL-33 (WNV) have been linked to neuroinflammation following virus infection, but no changes in their levels were observed in TBEV-infected CSF samples compared to controls." (PMID 40517242, 2025). "On the other hand, HCV-associated cNK cells showed a pro-inflammatory profile, with high expression of the chemoattractants CCL3, CCL4, and XCL1, and the ligand TNFSF9 (CD137L), a costimulatory signal that can induce CD8+ T cells response against viral infection." (PMID 37063898, 2023). "Similarly, the naïve macrophages became activated in response to the viral infection and expressed essential inflammatory molecules like IL-1β, CCL3, and CCL4." (PMID 35440562, 2022). "CCL2, CCL3, CCL4, and CCXL10 are produced in the lung in the early phase of lung inflammation, working as a chemotactic factor for macrophages, NK cells, and T cells during viral infection." (PMID 34851149, 2022). "The release of CCL3, CCL4, and CCL5 may promote the recruitment and activation of T cells during viral infection of the brain." (PMID 34399779, 2021). "For example, in the absence of viral infection, CXCL10 mRNA, MDA5 mRNA, CXCL10, IL-4, IL-13, CCL4, CCL5, CCL20 and CCL24 were negatively associated with FVC." (PMID 30463560, 2018). "In our longitudinal study, we found that, in the absence of viral infection, CXCL10, IL-4, IL-13, CCL4, CCL5, CCL20 and CCL24 were each negatively associated with FVC." (PMID 30463560, 2018). "Additionally, PDCoV infection increased the transcription of the chemokines CCL2, CCL4, CXCL9, CXCL10 and CXCL11, suggesting that these chemokines may contribute to the recruitment and regulation of macrophages or other inflammatory cells to the sites of virus infection." (PMID 35328701, 2022). "It is also remarkable that the viral infection activated expression of two molecules that are typically expressed by T cells, although CCR1 has been detected in a subpopulation of non-germinal center B cells and CCL4 is released after B cell receptor stimulation." (PMID 40389409, 2025).
Cirrhosis (30 papers, 1996 to 2025). A chronic disorder of the liver in which liver tissue becomes scarred and is partially replaced by regenerative nodules and fibrotic tissue resulting in loss of liver function. "In cases of HCC associated with MASLD-related cirrhosis, patients exhibited higher levels of fecal calprotectin and plasma levels of IL-8, IL-13, CCL3, CCL4, and CCL5 compared to those with MASLD-induced cirrhosis without HCC." (PMID 39451600, 2024). "Initially, we successfully induced a cirrhosis model using CCL4 and confirmed PVT formation using ultrasound." (PMID 37965548, 2023). "The NLRP3 inflammasome is significantly activated in a CCL4-induced mouse model of cirrhosis, which aggravates hepatocyte death and cirrhosis through the NLRP3/caspase-1/GSDMD classical pyroptosis pathway." (PMID 37370025, 2023). "Of the chemokines contributing to improved predictability of cirrhosis, CXCL10, CCL3, and CCL4 have been implicated in progression of liver disease." (PMID 36358697, 2022). "And we have provided evidence that oats a significant effect on biochemical assays in blood serum in rats with cirrhosis by CCL4." (PMID 34867017, 2021). "Nonetheless, serum IL-24 was undetectable in CCL4-treated mice and human cirrhosis and ALF patients, excluding its engagement as a “hepatokine” in UPR condition." (PMID 31907348, 2020). "We understand that there are chemicals other than DMN that can be used to induce cirrhosis, including CCL4, TAA, and GalN16." (PMID 32427847, 2020). "Our preclinical study aimed at developing a cirrhosis-PVT model in a large animal model (pig) that has CCL4-induced cirrhosis and depicting the changes of hepatic function, coagulation system, and inflammation cytokines." (PMID 32351989, 2020). "Because of the toxicity and prolonged exposure of CCL4, more mice had to be prematurely killed during the induction of cirrhosis (40%) compared to the induction of fibrosis (17%)." (PMID 31245923, 2019). "In addition, lower body weight, grip strength, and muscle tissue weight were noted in the CCL4‐induced cirrhosis group compared to the oil group." (PMID 39804962, 2025). "Similarly, a significant increase in MuRF1 expression was observed in the muscle tissue of mice with CCL4‐induced cirrhosis." (PMID 39804962, 2025). "Different groups were transplanted intravenously in the rat cirrhosis model induced by CCL4." (PMID 37226279, 2023). "CCL4 is most commonly used hepatotoxin in cirrhosis induction in rodents." (PMID 35328564, 2022). "The combination of CCL4, urethane and peanut oil was used to induce cirrhosis." (PMID 35328564, 2022). "Histology confirmed induction of hepatic cirrhosis with CCL4." (PMID 31359992, 2019). "Furthermore, we compared the therapeutic potential of MSCs and fibroblasts in a novel treatment strategy where mice with CCL4‐induced fibrosis and cirrhosis underwent a partial hepatectomy (pHx), as regeneration stimulus, and received concomitant cell therapy." (PMID 31245923, 2019). "Two biomarkers in this pathway, CCL4 and LAP-TGF-beta-1, also improved predictability of cirrhosis in the 12-marker CDA model." (PMID 36358697, 2022). "In our study, we show in two different animal models of cirrhosis (BDL and CCL4), that portal pressure is significantly elevated 2 and 7 days after IM vs. LAP (median laparotomy)." (PMID 34489738, 2021). "Excluding CCL-11, higher levels of chemokines CCL-3, CCL-4, CCL-5, CXCL-8, and CXCL-10 were observed in compensated cirrhosis patients compared to fibrotic and decompensated cirrhosis patients." (PMID 29977152, 2018). "BM-MSCs reduced the pathological effects of CCL4 induced hepatic cirrhosis and labelling BMMSCs with SPIONs were non-toxic and enabled efficient tracking using non-invasive methods." (PMID 31359992, 2019).
Cirrhosis (continued). "Significant weight differences were observed in all models of cirrhosis or non-cirrhotic portal hypertension at time of IM, compared to the respective control groups (Sham, Air), with a significantly lower body weight in the PPVL, BDL, and CCL4 groups at the time of IM vs. LAP." (PMID 34489738, 2021).
diabetes (29 papers, 2014 to 2025). "In the present study, we observed decreased differential expression of CCL4 and IL-18 at 60 days with prebiotic/probiotic supplementation, which given their associations should be associated with a reduced risk of type 2 diabetes mellitus." (PMID 36437471, 2022). "It is worth to underline that, CCL4 polymorphisms and protein levels correlate with the psoriasis course and can also play a role in the development and/or progression of diabetes mellitus and atherosclerosis." (PMID 34006909, 2021). "In particular, CCL3 and CCL4 encoding small CC chemokines known as macrophage inflammatory protein 1α and 1β, respectively, were well-recognized as key mediators of both diabetes and atherosclerotic cardiovascular disease." (PMID 28710368, 2017). "Increased levels of CCL4 in Yakutia may be associated with a lower incidence of diabetes and a higher incidence of nervous system diseases, and increased levels of CXCL10 in Yakutia, with a higher incidence of respiratory diseases." (PMID 39769502, 2024). "Although CCL4 typically increases in diabetes-related inflammation, our study, found reduced levels, possibly due to effective glycemic control." (PMID 41030257, 2025). "The significant reductions in serum concentrations of PD-L1, IL-1ra, and CCL4 suggest potential benefits of the intervention for obesity, with implications in many diseases such as diabetes, cancer, and autoimmune conditions." (PMID 40145019, 2025). "In a diabetes mellitus (DM) model, T cells are attracted to the place of insulitis via CCL4, and inhibition of CCL4 and IL-16 were protective from DM." (PMID 40529362, 2025). "One recent study also showed that CCL4 plays a significant role in glucose metabolism and is upregulated in diabetes mellitus." (PMID 37333648, 2023). "Elevated CCL4 and IL-18 result in elevated systemic inflammation and the onset and progression of type 2 diabetes mellitus." (PMID 36437471, 2022). "Oligonol inhibited NF-κB activation under different pathological conditions, including diabetes-induced kidney damage, diabetes, CCL4-induced liver injury, and dextran sulfate sodium-induced colitis in vivo." (PMID 28930190, 2017). "In another NOD mouse model, an elevated ratio of CCL3 to CCL4 in the pancreas was correlated with destructive insulitis and progression to diabetes." (PMID 27553774, 2016). "In this study, we have identified a group of APMB-specific analytes (IL-10, CXCL1, IL-12p40, IL-13, CCL22, CCL4, IL-17A, and TGFα) that correlates with several clinical phenotypes associated with more severe SAB (diabetes, dialysis dependence, metastatic infection, and cardiac vegetation)." (PMID 39966757, 2025). "Taken together, in most clinical diabetes patients, circulating CCL4 levels may be increased early with the dysfunction of β-cells, even before they are extensively damaged." (PMID 27553774, 2016). "In summary, while CCL3 contributes to the development of type 1 DM, CCL4 might play a protective role in some experimental diabetes, especially the NOD type 1 DM model." (PMID 27553774, 2016). "Though it may attract macrophages to destroy islet cells, CCL4 could play a protective role in some experimental diabetes models, especially the NOD type 1 DM model." (PMID 27553774, 2016). "However, some studies have observed increased CCL4 concentrations in patients in the prediabetic state with a tendency to decrease with insulin intake, which may indicate that CCL4 levels may differ at different stages of diabetes development or severity." (PMID 39769502, 2024). "CCL4 was upregulated in both people with T1D and T2D, and its inhibition had a protective effect on pancreatic beta-cells, increased insulin sensitivity, and delayed the progression of hyperglycaemia, suggesting the critical role of CCL4-related inflammation in the progression of diabetes." (PMID 36674502, 2023).
diabetes (continued). "While both TNF-α and IL-6 could be reduced by CCL4 inhibition, it will be interesting to elucidate whether a broader inhibition of systemic inflammation with a specific chemokine, such as CCL4, could improve insulin resistance in clinical diabetes." (PMID 33968046, 2021). "The levels of inflammatory markers, such as TNF-α and IL-6, which are the root causes of insulin resistance in type 2 diabetic patients with type 2 diabetes, were decreased in the CCL4 antibody injection group, compared with those in the IgG-treated DM group." (PMID 33968046, 2021). "However, the role of CCL4 is much less clear in type 2 DM and might be varied in different animal models of experimental diabetes." (PMID 27553774, 2016). "Being a major macrophage attractant, universal involvement of CCL4 has been found in diabetes mellitus, since its circulating concentration increased regardless of disease stage, which may contribute to destruction of islet cells and the progression of diabetes." (PMID 34975900, 2021). "Indeed, the in vivo pathogenesis role of CCL4 in experimental diabetes may be obscured." (PMID 27553774, 2016). "Corresponding to our global correlation analyses, APMB patients with diabetes had lower levels of IL-13 and trended toward decreased CCL4 as compared to those who did not." (PMID 39966757, 2025). "Our results on CCL 4 are mostly consistent with previous studies, which reported higher levels of CCL4 in all types of diabetes, although there was no segregation of the subjects on the basis of gender or BMI." (PMID 39063997, 2024). "The circulating concentrations of CCL4 do not differ between patients with type 1 and type 2 diabetes, suggesting a general involvement of CCL4 in different types of diabetes." (PMID 33968046, 2021). "Therefore, the goal of our study was to evaluate the participation of macrophage inflammatory protein-1 (MIP-1) family members (CCL3, CCL4, CCL9) in a streptozotocin (STZ)-induced mouse model of diabetic neuropathic pain." (PMID 29593735, 2018). "In NOD.Scid recipients, the neutralization of CCL3 with specific antibodies following transfer of diabetogenic T cells delayed the onset of diabetes, while the injection with anti-CCL4 mAb did not." (PMID 27553774, 2016). "Clinically, the role of CCL4 in diabetes has not yet been well established; however, study on diabetic patients with and without diabetic retinopathy has shown that in retinal glial cells, the CCL4 protein level is lower in diabetic patients without diabetic retinopathy than in controls." (PMID 39457105, 2024). "Moreover, a decreased intra-pancreatic CCL3 to CCL4 ratio was also observed in nonobese diabetes-resistant mice." (PMID 27553774, 2016). "However, the current CCL4 data are not consistent, especially for the complications of diabetes." (PMID 27553774, 2016). "Interestingly our Ecuadorian “healthy” control group indeed had higher levels of CCL4 and IL-6, suggesting that in particular obesity and dyslipidemia determine a higher level of these classical pro-inflammatory cytokines in serum, and not (only) the diabetes state and/or pathology per se." (PMID 25500583, 2014).
Obesity (29 papers, 2012 to 2025). Accumulation of substantial excess body fat. "CCR5, the most well-known receptor of CCL4, is linked with obesity, inflammation, and insulin resistance." (PMID 33968046, 2021). "CCL4 directly contributes to the obesity-associated metabolic inflammation by influencing the migration and recruitment of monocytes into the adipose tissue." (PMID 31546972, 2019). "Finally, IL6 and CCL4 were confirmed as the hub genes associated with both obesity and GC." (PMID 39011399, 2024). "Amongst the factors that exhibited statistically significant differences between the lean and obese groups with obesity at T3 were myeloid factors, including CCL4, IL-1β, IL-1RA, and IL-27." (PMID 34195568, 2021). "CCL4, also referred to as macrophage inflammatory protein-1β (MIP-1β), is considered a major macrophage attractant that causes obesity-induced chronic inflammation and insulin resistance." (PMID 34360840, 2021). "At T1, obesity was associated with a 2-fold increase of myeloid cell chemoattractants CCL2 and 1.5-fold increase in circulating CCL4." (PMID 34195568, 2021). "CCL3 and CCL4 are machophage-derived inflammatory proteins belonging to the CC-motif cytokine family, that show increased expression in diabetic patients and obesity." (PMID 33526854, 2021). "The CC chemokine family members CCL3 and CCL4 have both tens of publications where obesity is mentioned, but with debate on the mechanisms involved and function." (PMID 33204460, 2020). "We saw in the immunometabolism component that obesity and known related clinical variables associated with elevated levels of cytokines TRANCE, CCL4, IL18R1, CCL3 and FGF21, for which known links to obesity were discussed." (PMID 33204460, 2020). "Elevated CCL4 levels were reported in obesity and found to be correlated directly with metabolic inflammation." (PMID 31546972, 2019). "Increased circulatory levels of TNF-α, palmitate and CCL4 are co-expressed in obesity." (PMID 31546972, 2019). "Given that accumulating evidence points to the co-existence of increased circulatory levels of TNF-α, palmitate and CCL4 in obesity/T2D, we asked whether TNF-α and palmitate could cooperatively trigger the CCL4 production in human monocytic cells." (PMID 31546972, 2019). "IL6 and CCL4 may play important roles in the microenvironment of obesity and GC." (PMID 39011399, 2024). "Thus, further research is needed to determine whether CCL4 is connected to hypersensitivity related to obesity." (PMID 39457105, 2024). "However, mechanisms triggering the CCL4 levels in obesity are poorly understood." (PMID 31546972, 2019). "Other chemokines include but not limited to CCL2 (MCP-1), CCL3 (MIP-1α), CCL4 (MIP-1β), CCL19, CXCL1, CXCL8 or IL-8, CXCL10, and CXCL12 also play an important role in obesity and cancer immunotherapy." (PMID 40863244, 2025). "Elevated CCL4 and CCL2 expression were observed in subcutaneous adipose tissue cells isolated from patients with obesity compared with those in patients with normal body weight." (PMID 40145019, 2025). "Elevated CCL4 and CCL2 expression levels were reported in obesity and found to be correlated with inflammation and insulin resistance." (PMID 35412419, 2022). "This study was a secondary analysis of a single-arm weight loss clinical trial for adults with obesity, which aimed to investigate the effects of ADF-LC on circulating immune response biomarkers that are modulated by obesity including PD-L1, CCL2, CCL4, IL-8, IL-1ra, IFNγ, CD40-L, and IP-10." (PMID 40145019, 2025). "Using a T2DM and a control cohort from the Asir region of Saudia Arabia, we looked into the association between the pro-inflammatory chemokines CCL1, CCL2, CCL4, and CCL5 and the etiopathogenesis of T2DM in subjects with different degrees of obesity, BMI, and HbA1c." (PMID 39063997, 2024).
Obesity (continued). "With this background, we intend to study the relationship between pro-inflammatory chemokines CCL1, CCL2, CCL4, and CCL5 and the etiopathogenesis of T2DM in subjects with varying levels of obesity, BMI, and HbA1c in a patient cohort from the Asir region of Saudia Arabia." (PMID 39063997, 2024). "Interestingly, spontaneous (in the absence of stimulation) production of several chemokines (IL-8, CXCL10, Eotaxin, CCL4, and CCL2) was significantly reduced with pregravid obesity." (PMID 30131724, 2018).